TRPC6 (transient receptor potential cation channel subfamily C member 6)
Diseases named in the same sentence as TRPC6 in open-access papers (continued):
Sharing a sentence is not in itself a finding about the gene and the disease.
idiopathic pulmonary arterial hypertension (13 papers, 2010 to 2023). A sporadic form of pulmonary arterial hypertension (PAH) characterized by elevated pulmonary arterial resistance leading to right heart failure. "Increased TRPC6 promoter activity and TRPC6 expression have been linked to the development of idiopathic pulmonary arterial hypertension, which is caused by excessive proliferation of pulmonary artery smooth muscle cells." (PMID 32350291, 2020). "Inhibition of nuclear factor-kappa-B activity attenuated TRPC6 expression and decreased agonist-activated Ca2+ influx in pulmonary artery smooth muscle cells of idiopathic pulmonary arterial hypertension patients harboring the -254G allele." (PMID 28197477, 2015). "Increased expression of TRPC6 was implicated in the pathogenesis of idiopathic pulmonary arterial hypertension (IPAH)." (PMID 24709960, 2014). "Another SNP in the TRPC6 promoter region (rs3824934) was revealed to cause idiopathic pulmonary arterial hypertension (IPAH) via facilitating the binding of NF-κB to the promoter and enhancing the expression of TRPC6." (PMID 31936014, 2020). "Another example involving enhanced expression of wild type TRPC6 and disease was found in idiopathic pulmonary arterial hypertension in humans." (PMID 20877463, 2010). "TRPC6 is highly expressed in PASMCs in patients with idiopathic pulmonary arterial hypertension (iPAH) and is involved in PASMC proliferation by initiating and promoting cell cycle growth, and by triggering gene transcription via transcription factor phosphorylation." (PMID 38033335, 2023). "In lung, another current subject in search for treatment options, increased TRPC6 responses of smooth muscle and vascular endothelial cells are associated with acute hypoxic vasoconstriction but also with idiopathic pulmonary arterial hypertension (IPAH) and lung ischemia-reperfusion edema (LIRE)." (PMID 35408998, 2022). "Firstly, TRPC6 expression is upregulated in human PA from PH patients and PASMC from idiopathic pulmonary arterial hypertension (IPAH) patients, as well as in PH animal models such as CH and MCT." (PMID 34572602, 2021). "In fact, mRNA and protein expression of TRPC6 in lung tissues and PASMCs from patients with idiopathic pulmonary arterial hypertension (IPAH), which develop the disease due to unknown reasons, is much higher than in those from normotensive patients." (PMID 30717260, 2019). "Furthermore, a unique genetic variation in the TRPC6 gene promoter has been identified, which might link the inflammatory response to the upregulation of TRPC6 expression and ultimate development of pulmonary vascular abnormalities in idiopathic pulmonary arterial hypertension." (PMID 28670316, 2017).
Nephropathy (13 papers, 2013 to 2025). A nonspecific term referring to disease or damage of the kidneys. "Previous studies demonstrated that TRPC6 channels play a pivotal role in podocyte function and their dysregulation is associated with development of different kidney diseases including nephropathy." (PMID 37108424, 2023). "The decisive contribution of TRPC6 channels to the pathological Ca2+ signaling in the kidney has been demonstrated in many studies, especially in the studies of genetically inherited TRPC6 mutations that cause nephropathy." (PMID 37108424, 2023). "Longitudinal studies are needed to assess the accuracy of TRPC6 during the pre-clinical stages of DN to predict the progression of nephropathy to clinical proteinuria and the progressive loss of renal function." (PMID 24103534, 2013). "A study has shown that TRPC6 rs3824934 C > G mutation may increase the transcription and expression of TRPC6, which may be implicated in the development of steroid-resistant nephropathy." (PMID 34512318, 2021). "The present study suggests that TRPC6 contributes to the deleterious effects of a PON2 knockout in the adriamycin-induced nephropathy mouse model, at least at early stages of the disease." (PMID 36429053, 2022). "We confirmed that this mechanism also acts in vivo, as eNOS KO mice showed higher glomerular TRPC6 protein expression levels than WT mice upon the induction of Adriamycin-induced nephropathy." (PMID 34830371, 2021). "We also investigated if NO prevented glomerular TRPC6 overexpression during Adriamycin-induced nephropathy in vivo." (PMID 34830371, 2021). "Ziying Wang, etc. showed that the NOX4 -derived ROS up-regulates TRPC6 expression in puromyc in aminonucleoside-induced nephropathy, which subsequently regulates the intracellular calcium homeostasis." (PMID 25203114, 2014). "ATRA may alleviate proteinuria by down-regulating TRPC6 expression in nephropathy rats." (PMID 29619864, 2018). "Thus, in line with our finding that sGC stimulation by NO decreases the expression and activity of TRPC6 during Adriamycin-mediated podocyte injury in vitro, the absence of NO leads to enhanced glomerular TRPC6 expression in a mouse strain normally resistant to Adriamycin-induced nephropathy." (PMID 34830371, 2021). "The TRPC6 mRNA level was increased by 78 ± 28% in glomeruli from diabetic rats, which coincides with data on TRPC6 expression obtained earlier in FGSS nephropathy and in rats with diabetes type 1." (PMID 37108424, 2023). "Therefore, we measured glomerular TRPC6 expression in C57BL6/6J WT and C57BL6/6J eNOS KO mice after inducing nephropathy with Adriamycin." (PMID 34830371, 2021).
Cerebral ischemia (12 papers, 2017 to 2022). Restriction of arterial blood supply to the brain associated with insufficient oxygenation to support the metabolic requirements of the tissue. "Cerebral ischemia is associated with intracellular calcium overload leading to activation of calpain, which hydrolyzes TRPC6." (PMID 32477327, 2020). "Dysregulation of TRPC6 activity has been implicated in ischemic stroke, as well as retinal ischemia, and renal hypoxia following cerebral ischemia." (PMID 33114455, 2020). "Trpc6-transgenic mice with an elevated basal level of TRPC6 expression are less susceptible to cerebral ischemia than their wild-type littermates and have lower mortality rates, reduced infarct volumes, and better neurological outcomes after middle cerebral artery occlusion (MCAO)." (PMID 33114455, 2020). "In this study, the expression of DMT1, LTCC, and TRPC6 increased after 2 hours of cerebral ischemia reperfusion in rats." (PMID 35958925, 2022). "Current prevalent evidence suggests that the TRPC6 channel function is downregulated in AD and cerebral ischemia." (PMID 33114455, 2020). "In several studies, TRPC6 in neurons reportedly declines after cerebral ischemia, and maintaining the expression of neuronal TRPC6 protein contributes to neuronal survival and reduced cerebral ischemic insult." (PMID 33604333, 2020). "This review is devoted to the description of the role of TRPC6 channels in AD and brain ischemia with a particular focus on the dysfunction of them as Ca2+-dependent channels." (PMID 33114455, 2020). "Contrary, cerebral ischemia-induced rat cortical neuron TRPC6 degradation, oxidative stress and apoptosis were reduced at 24 h of cerebral ischemia by hyperforin treatment." (PMID 28620309, 2017). "The mechanism of IL-17-induced damage following ischemia is not fully understood; however, one study demonstrated evidence of increased activation of the calpain-transient receptor potential canonical (subtype) 6 (TRPC6) signaling pathway, which is known to be involved in cerebral ischemia." (PMID 32477327, 2020). "In turn, the development of selective TRPC6 channel modulators could help slow down the progression of AD, cerebral ischemia, and, most likely, other TRPC6-dependent diseases." (PMID 33114455, 2020). "However, there are reports in the literature that observe TRPC6 overactivation in AD and cerebral ischemia models." (PMID 33114455, 2020). "Accumulating evidence supports the important functions of TRPC6 in brain ischemia." (PMID 32256338, 2020). "However, similarly to AD, brain ischemia seems to be heterogenic, meaning that one group of patients has TRPC6 hypofunction, and another one has TRPC6 hyperfunction." (PMID 33114455, 2020). "Furthermore, this review concentrates on evidence-based advancements of TRPC6 in CNS disorders and cerebral ischemia." (PMID 32256338, 2020). "The results indicated that TRPC6 channel may mediate the neuroprotection of calycosin after cerebral ischemia injury." (PMID 28596571, 2017). "However, activation of calpain leads to TRPC6 degradation and contributes to neuronal damage in cerebral ischemia." (PMID 28596571, 2017). "Suppression of TRPC6 degradation may therefore be useful in cerebral ischemia to preserve neurons." (PMID 32477327, 2020). "In addition, we used a TRPC inhibitor, SKF96365 to investigate whether TRPC6 is critical in calycosin-induced protection against cerebral ischemia." (PMID 28596571, 2017). "The imbalance between iron input proteins DMT1, LTCC, TRPC6, and output protein FPN1 is considered to be the main trigger of brain iron disorder after cerebral ischemia." (PMID 35958925, 2022). "There are studies reporting that TRPC6-mediated Ca2+ and Na+ influx facilitates NMDAR activation and exacerbates excitotoxicity, while TRPC6 deletion attenuates neuronal damage and death following focal cerebral ischemia." (PMID 33114455, 2020).
Cerebral ischemia (continued). "Taken together, our studies demonstrated that calycosin blocked calpain-mediated degradation of TRPC6 channel that modulate intracellular Ca2+ levels to stimulate CREB phosphorylation, resulting in neuroprotection against cerebral ischemia in both in vivo and in vitro models." (PMID 28596571, 2017).
Cognitive impairment (12 papers, 2020 to 2025). Abnormal cognition is characterized by deficits in thinking, reasoning, or remembering. "Clinically, dysfunction of TRPC6 was closely associated with cognitive impairment in type 2 diabetic patients with RH." (PMID 33135341, 2020). "Finally, clinical data prove that TRPC6 dysfunction is associated with cognitive impairment in type 2 diabetic patients." (PMID 33135341, 2020). "Therefore, TRPC6 is essential for the beneficial effect of hyperforin on RH‐caused cognitive impairment despite hyperforin also has other protective effects unrelated to TRPC6." (PMID 33135341, 2020). "The results indicate that the TRPC6 agonist is efficient in ameliorating CH‐mediated cognitive impairment of pups." (PMID 40994415, 2025). "The TRPC6 agonist hyperforin is efficient in promoting growth of neuronal dendritic spines and ameliorating cognitive deficits of the CH pups." (PMID 40994415, 2025). "As such, it is reasonable to observe that CH‐mediated cognitive impairment is partially ameliorated by the TRPC6 activator." (PMID 40994415, 2025). "Supporting to this finding, activation of GLUT3 by transient receptor potential channel 6 (TRPC6) attenuates hypoglycaemia-induced cognitive impairment." (PMID 38977507, 2024). "This demonstrates that TRPC6 inactivation is an aggravating feature for hypoglycemia-induced cognitive impairment, and a protective feature in cases of its activation, making TRPC6 a potential therapeutic target." (PMID 37372995, 2023). "A positive allosteric modulator of TRPC6, benzopyran derivative C20, efficiently recovers cognitive deficit in 6-month-old 5xFAD mice in the contextual and tone fear conditioning test." (PMID 37895105, 2023). "Taken together, RH impairs brain GLUT3-mediated glucose uptake and further provokes neuronal mitochondrial dysfunction by inhibiting TRPC6 expression, which then accelerates progression of cognitive deficits in diabetic APP/PS1 mice." (PMID 35077394, 2022). "We have recently reported that TRPC6 is a critical sensitive cation channel to hypoglycemia and a promising target for preventing RH-induced cognitive impairment." (PMID 35077394, 2022). "We have recently shown that a RH-induced reduction in TRPC6 expression led to cognitive impairment under diabetic conditions by impairing hippocampal mitochondrial function." (PMID 35077394, 2022). "TRPC6 activation enhances Glut3-mediated glucose uptake in the brain and alleviates RH-induced cognitive deficits." (PMID 35077394, 2022). "Overall, down-regulation of TRPC6 expression in the hippocampal DG region of adult-aged mice by way of AAV virus injection leads to similar or worse cognitive impairment." (PMID 34327201, 2021). "In fact, a recent study observed that hyperforin induced activation of TRPC6, reduced Aβ levels, and improved mild cognitive impairment in AD models and that TRPC6 mRNA levels in the blood cells were reduced in AD patients." (PMID 33748103, 2021). "The down-regulation of TRPC6 protein in the DG region on cognitive impairment has been demonstrated in this study." (PMID 34327201, 2021). "Recurrent moderate hypoglycemia disturbs mitochondrial morphology and function in hippocampus by inhibiting TRPC6, leading to neuronal death and cognitive impairment in diabetic mice." (PMID 33135341, 2020). "Here, we provide experimental and clinical evidence to identify TRPC6 as a potential intervention target for RH‐induced cognitive impairment in diabetic patients." (PMID 33135341, 2020). "We elucidated the molecular mechanism of RH‐induced cognitive impairment and identified TRPC6 as an important target in response to hypoglycemic stimulation in the brain." (PMID 33135341, 2020). "The activation of TRPC6 by hyperforin significantly improved RH‐induced cognitive impairment and mitochondrial dysfunction and these favorable impacts were absent in TRPC6 knockout mice." (PMID 33135341, 2020).
Cognitive impairment (continued). "Our results indicate that TRPC6 is a critical sensitive cation channel to hypoglycemia and is a promising target to prevent RH‐induced cognitive impairment by properly orchestrating the mitochondrial dynamics in diabetic patients." (PMID 33135341, 2020). "The results have unveiled novel roles of TRPC6 in regulating CH‐mediated cognitive deficits." (PMID 40994415, 2025). "A vast variety of central nervous system (CNS)-related diseases such as epilepsy, autism spectrum disorder and AD are characterized by cognitive impairments and may be provoked by TRPC6 malfunctions." (PMID 37895105, 2023). "Some other TRPC6 activators have been demonstrated to improve cognitive impairments." (PMID 37895105, 2023). "Moreover, reduction of TRPC6 expression was found in patients with AD and mild cognitive impairment, which negatively correlated with the cognitive performance." (PMID 36224261, 2022). "Activation of TRPC6 with hyperforin substantially improved RH‐induced cognitive impairment." (PMID 33135341, 2020). "Here, we demonstrated that the beneficial effect of hyperforin on RH‐induced mitochondrial dysfunction and structural damage was also relied on TRPC6 activation, further demonstrating that RH promoted hippocampus mitochondrial fission and cognitive impairment in diabetic mice by repressing TRPC6." (PMID 33135341, 2020). "We found that the repressed TRPC6 is related to the cognitive impairment caused by RH, and the absence of TRPC6 directly led to cognitive dysfunction in STZ‐induced type 1 diabetic mice." (PMID 33135341, 2020). "TRPC6 might be a promising target for the prevention and treatment of hypoglycemia‐related cognitive impairment in diabetic patients." (PMID 33135341, 2020). "However, whether and how TRPC6 participates in RH‐induced cognitive impairment remain uninvestigated." (PMID 33135341, 2020). "Moreover, activation of TRPC6 by hyperforin remarkably recovered cognitive function in diabetic mice experienced RH attack, implying that TRPC6 acts as a guardian protecting against RH‐induced cognitive impairment." (PMID 33135341, 2020). "Thus, TRPC6 dysfunction might be a major step for cognitive impairment in diabetic patients with RH." (PMID 33135341, 2020). "Activation of the transient receptor potential channel 6 (TRPC6) increased GLUT3-mediated glucose uptake in the brain and alleviated RH-induced cognitive deficits, and inactivation of the Ca2+/AMPK pathway was responsible for TRPC6-induced GLUT3 inhibition." (PMID 35077394, 2022). "Thus, hypoglycaemia-induced cognitive impairment and AD-like pathology are mediated by the inhibition the expression of the GLUT3/TRPC6 pathway in the brain." (PMID 38977507, 2024). "TRPC6 knockout directly led to cognitive impairment in diabetic mice to an extent similar to RH and RH failed to further impair cognitive function in TRPC6−/− diabetic mice." (PMID 33135341, 2020).
glioblastoma (12 papers, 2011 to 2025). The most malignant astrocytic tumor (WHO grade IV). "TRPC6 is linked to several cancer types such as prostate, lung and colon cancer as well as glioblastoma." (PMID 29772843, 2018). "Under hypoxia, TRPC6 causes a sustained elevation of intracellular calcium that is coupled with the development of malignant glioblastoma multiforme cells." (PMID 27011063, 2016). "As one of HIF-1α’s target genes is glucose transporter I (GLUT1), inhibition of TRPC6 reduced glucose uptake during hypoxia, thus exhibiting its role as a significant metabolic regulator of glioblastomas." (PMID 36768856, 2023). "Consequent increase in TRPC6-mediated Ca2+ entry has also been found to alter the Notch pathway, leading to tumorigenesis in human glioblastoma multiforme (GBM) and GBM-derived cell lines." (PMID 35359398, 2022). "In human glioblastoma cells, TRPC6 expression is augmented by hypoxia and increases proliferation and cell invasion." (PMID 29772843, 2018). "Here, TRPC6 is suggested to be a key mediator of Notch-driven glioblastoma invasiveness and angiogenesis." (PMID 29772843, 2018). "On the other hand, in glioblastoma multiforme, the most common primary brain tumor in humans and one of the most angiogenic tumors, TRPC6 expression is markedly upregulated compared to normal brain tissue." (PMID 24204345, 2013). "Furthermore, in vitro studies in glioblastoma cells demonstrated enhanced radiosensitivity with TRPC6 inhibition, while activation of TRPV2 channel increased chemosensitivity of cells." (PMID 30691160, 2019). "In another study, hypoxic upregulation of TRPC6 expression (via Notch signaling), resulted in activation of nuclear factor of activated T-cells (NFAT), proliferation, invasion and angiogenesis of glioblastoma cells." (PMID 30691160, 2019). "Inhibition of TRPC6, by shRNA or expression of its dominant-negative mutant (DNC6), abolished hypoxia-induced HIF-1α protein accumulation in U251 human glioblastoma cells via promotion of HIF-1α hydroxylation." (PMID 30691160, 2019). "Previously, it has been demonstrated that hypoxia could drive glioblastoma multiforme cells into a more aggressive and malignant state through Notch1-induced TRPC6 overexpression which in turn activated the calcineurin-nuclear factor of activated T-cell (NFAT) pathway and increased Ca2+ influx." (PMID 28400714, 2017).
renal failure (12 papers, 2009 to 2025). "Since this is the first time that a TRPC6 mutation is shown to cause early-onset FSGS, it is required to consider mutated TRPC6 as a possible cause for renal failure in children." (PMID 19936226, 2009). "TRPC6 gene variations have been linked to chronic kidney disease but its role in acute kidney injury (AKI) is unknown." (PMID 35194063, 2022). "The TRPC6 KO PAR-1 mice live longer than the PAR-1 TRPC6 WT mice but still die prematurely of renal failure." (PMID 36940798, 2023). "A human with a TRPC6 mutation may experience renal failure in the third decade of life, which would be considered quite young relative to a normal human lifespan, and yet an adult mouse constitutively over-expressing the same TRPC6 variant may barely show any effects." (PMID 36421724, 2022). "In addition, it was reported that TRPC6 did not play a role in the acute phase of acute kidney injury." (PMID 41009007, 2025). "None of the 13 identified TRPC6 sequence variations correlated with remission or renal failure." (PMID 25019165, 2014).